IFNG (interferon gamma)
Diseases named in the same sentence as IFNG in open-access papers (continued):
Sharing a sentence is not in itself a finding about the gene and the disease.
infection (continued). "Fibrin deposition is associated with infection, where it protects against IFNG-mediated hemorrhage." (PMID 38882332, 2024). "Moreover, homozygosity for common TYK2 missense variants, including variants encoding catalytically inactive TYK2, impairs IL-23-dependent IFNγ production and predisposes patients to infections with Mycobacterium tuberculosis." (PMID 39622833, 2024). "Indeed, Ser/5-HT signaling fuels the infection of astrocytes by T. cruzi, a process potentiated by IFNγ and TNF and linked to a neurotoxic milieu enriched in NO and glutamate." (PMID 38776344, 2024). "Infection with the dimorphic endemic fungus Histoplasma capsulatum has mainly been associated with anti-IFNγ auto-antibodies, although three cases in patients with PAP (and, therefore, likely positive for anti-GM-CSF auto-antibodies) have been reported as well." (PMID 38203686, 2023). "moshkovskii infection might be due to downregulation of IFNγ production caused by parasitic activation of an antagonistic Th2-type immune response." (PMID 37111135, 2023). "We hypothesized that the high evolutionary selective pressure for the KRKR motif of IFNγ is associated with chronic antigen stimulation, as occurs during infections with delayed pathogen elimination." (PMID 36732425, 2023). "While other stimuli, such as bacterial lipopolysaccharide (LPS), simulate infection-associated defense mechanisms and trigger microglia-mediated neurotoxicity, IFNγ is a sterile stimulus actively involved in AD pathology, with a neuroimmune role over microglia activation and synaptic activity." (PMID 35620289, 2022). "However, IFNGR1- and IFNG/IFNGR1-deficient cell lines maintained relatively low levels of IFN-γ-responsive cytokines upon HSV-1 or HCoV-OC43 infection." (PMID 35897807, 2022). "Therefore, it is significant that we also identified that variation in both STAT2 and IFNγ is associated with infection resolution in the koala." (PMID 35510793, 2022). "Groups of both wild-type (C57BL/6J) and IFNγ deficient mice were included in the study; the IFNγ deficient (KO) mice are highly susceptible to T. cruzi infection and were expected to reveal even very low levels of persistent infection." (PMID 36315597, 2022). "As a marker of cell-mediated immune response generated through vaccination and natural infection, we have used T cell-associated IFNγ and CD40L in line with the involvement of these molecules in sustaining the recall immune response generated upon antigenic stimulation of already primed T cells." (PMID 37304053, 2022). "Following infection, interferon γ (IFNγ) is upregulated and experimental infections showed higher weight loss and pathology but lower oocysts shedding in IFNγ‐deficient mice than in wild type." (PMID 35571751, 2022). "Nkp46+ RORγt+ ILC-derived IFNγ is required for bacterial clearance, however it can also cause epithelial damage, since Tbx21−/− and IFNγR1−/− mice exhibit a decrease in intestinal pathology 48h post infection with Salmonella." (PMID 36430676, 2022). "The increased IFNγ signalling found here in RhD-negative males may begin to explain their reduced susceptibility to infection." (PMID 35428875, 2022). "In vitro IFNγ production, a novel functional marker of cell-mediated immune response, is being increasingly employed in immunocompromised transplant patients to assess their risk of infection and adverse outcomes." (PMID 36016305, 2022). "Notably, apoptosis, coagulation, and NFκB signaling were associated with the transcriptomic response to WT infection, whereas pathways linked with IFNα and IFNγ signaling were associated with ΔΔstx infection." (PMID 33529199, 2021). "In contrast, module 3 (M3) segregated in a different cluster of cytokines that include low IL-1β, IL-2, IL-12, moderate IL-17, IL-21, and high IFNγ, GM-CSF that were associated with low levels of lymphocytes and low titers of total IgG and IgG1 in the acute phase of infection." (PMID 33815363, 2021).
infection (continued). "However, RARRES3 deficiency partially alleviated IFNγ-mediated restriction of CTG-GFP infection and this deficiency was complemented with RARRES3 ectopic expression." (PMID 34871166, 2021). "SIT and the interferon-gamma test are both markers of cellular immunity in the early stage of infection, while ELISA (detection antibody in serum sample) is indicated as a diagnostic method for relatively later infection." (PMID 34138867, 2021). "Studies of mice and ex vivo human PBMC have shown that IFNG levels increase in response to schistosome antigens and are correlated with resistance or tolerance to infection and a candidate gene study found an association between the IFNG SNP rs2430561 and time to reinfection." (PMID 33659002, 2021). "Taken together, these results demonstrate classical activation of immune cells and infection-associated pathways that supports previous research as well as previously unknown kinetics of IFNγ-dependent signaling mechanisms." (PMID 33816350, 2021). "As we had observed low levels of IFNγ in the circulation of Il15ra-/- mice, we asked whether depletion of IFNγ prior to infection rendered them susceptible to low dose L. monocytogenes." (PMID 34956227, 2021). "Administration of IFNγ partially enabled IL-15-deficient mice to control the infection." (PMID 34956227, 2021). "Additionally, our recent data indicated that inactivation of T-bet in NKp46+ ILCs reduced intestinal pathology highlighting the pathogenic role of IFNγ+ ILCs during early stages of infection." (PMID 33488580, 2020). "We identified an IFNγ-dependent Type 1 immune gene signature as early as 2 days post infection (dpi) that was associated with a previously unidentified accumulation of IL-7Rα(CD127)−Eomesodermin (Eomes)+ natural killer (NK) cells at the site of infection." (PMID 31776431, 2020). "CON subjects had higher TRYP than SCZ, and we anticipated that TOXO infection would be associated with a lower TRYP because TOXO infection elicits an immune response that relies on induction of the cytokine IFNγ, which in turn inhibits TOXO replication by depletion of TRYP." (PMID 33329089, 2020). "Furthermore, IFNγ-deficient C57BL/6 mice succumb to the infection with a normally sublethal dose of R. conorii." (PMID 33091016, 2020). "IFNγ is vital for controlling various pathogenic infections early after infection and may restrict S. Typhimurium infection by limiting the availability of iron for intracellular S. Typhimurium or triggering the death of infected cells." (PMID 31134022, 2019). "More recent studies performed in a peritoneal infection model, have demonstrated that IFNγ acts both by promoting tissue-recruited monocyte differentiation into IL-12 producing DC at site of infection and the loss of resident mononuclear cell population which are not able to control infection." (PMID 31354722, 2019). "Gene ontology enrichment analysis of these identified genes indicated that pYSTAT5 activation in IECs up-regulated intestinal innate immunity, cytokine production, IFNγ, and autophagy, and down-regulated chromatin silencing, susceptibility to infection, and DNA damage–induced senescence." (PMID 30948494, 2019). "Interestingly, although the principal cytokine controlling Tg-infection is IFNγ, other cytokines have been implicated." (PMID 31830133, 2019). "Interferon gamma (IFNγ) plays a pivotal role in antimicrobial defense, and loss‐of‐function mutations in IFNγ‐receptor signaling in the human and mouse result in severe susceptibility to infections, including by bacteria and microbial parasites." (PMID 31268602, 2019). "Neutralization of TNF or IFNγ during a primary Lm-gp61 infection resulted in dramatically increased susceptibility to infection in LCMV-naïve mice, indicating that neutralization of either cytokine was sufficient to reduce protection from a primary response (data not shown)." (PMID 29438281, 2018).
infection (continued). "For example, cellular prion protein has been implicated in the optimal production of T cell cytokines since T cells from cellular prion protein-deficient mice generate less IFNγ, IL-4, and IL-17 in response to TcR-stimulation and have altered responses to infection and autoantigens." (PMID 30533413, 2018). "Infection of IFNγ deficient mice with systemic MHV caused a disease virtually identical to FIP." (PMID 30086792, 2018). "Moreover, a higher proportion of these CD4+ T cells from PE243-infected mice produced IFNγ and in a lesser extent IL-17, while infection caused a reduction of CD4+ T cells producing IL-4." (PMID 30087337, 2018). "We thus next asked whether reduced bacterial burdens and heightened IFNγ responsiveness seen in fGR1 monocytes during systemic in vivo infection might be associated with improved ability of myeloid cells to restrict L. monocytogenes to phagosomal compartments." (PMID 28542482, 2017). "The inability of IFNγ gene-knockout mice to control C. parvum infection was associated with reduced recruitment of macrophages and T cells to the lamina propria following infection suggesting they play an important role in control of infection in mice." (PMID 28800747, 2017). "Furthermore, C57BL/6 mice that are resistant to rickettsial infections show enhanced NK cell activity and IFNγ production early in the infection with R. conorii compared to susceptible C3H/HeN mice." (PMID 28770333, 2017). "On the other hand, IFNγ was critical to control parasite burden, indicating that the mechanisms underlying host resistance to infection may also impact hematopoietic function when sustained over time." (PMID 28671989, 2017). "In lymph nodes that drain infected tissues, prompt lymphocyte-macrophage communication, involving rapid production of IFNγ from resident lymphocytes and release of interleukin-18 from proximally associated macrophages, is crucial to limit the spread of infection." (PMID 28830544, 2017). "Furthermore, depletion of NK cells led to reduced IFNγ release and enhanced susceptibility of C3H/HeN mice to the infection with R. conorii, suggesting the contribution of NK cells to early defense against rickettsiae via the release of IFNγ." (PMID 28222146, 2017). "Indeed, it has been reported that mice in which the IFNγ gene has been deleted are much more susceptible to the infection than wild-type mice." (PMID 26999357, 2016). "However, in the Ft infection model we observed no decrease in Th2 cytokines such as IL-4 or IL-10 in Nlrp3-deficient mice at any time following infection, but IFNγ production was slightly elevated at 6 days post-infection." (PMID 27926940, 2016). "Furthermore, a strongly enhanced susceptibility of C57BL/6 IFNγ-/- mice for the infection with R. australis was observed." (PMID 27875529, 2016). "In striking contrast, IFNγ-deficient neonates die rapidly, within 7 days of infection." (PMID 28119902, 2016). "Under inflammatory conditions, for example, following an infection, M1 macrophage activation is induced by pathogen associated molecular patterns (PAMPs) such as lipopolysaccharide (LPS) in cooperation with interferon gamma (IFNγ)." (PMID 26977415, 2016). "Besides, our results are also in concordance with a previous study performed by our group reporting an association between IFNG and susceptibility to infection by T. cruzi." (PMID 27027876, 2016). "This “autoregulatory” population consists predominantly of IL10/IFNγ co-producing cells that express the canonical Th1 transcription factor Tbet and appear to be short-lived in the periphery, exhibiting a strong association with recent infection." (PMID 26182204, 2015). "Indeed, IFNγ is crucial for macrophage activation and optimal initiation of the type 1 immune response associated with resistance to infection." (PMID 26070118, 2015).
infection (continued). "By applying this approach to two pilot patients with disparate infections, we have determined that their contrasting growth patterns correlate with strikingly distinct transcriptional biomarkers, and are associated with differences in local levels of IFNγ." (PMID 24959423, 2014). "NK cell can also be pathogenic in the lung during infection from overproduction of IFNγ." (PMID 25197644, 2014). "Finally, in highly exposed HIV seropositive women, a low CD4 count is associated with low C. trachomatis-induced IFNγ production, and increased the risk of infection spread to the upper reproductive tract and PID." (PMID 24918090, 2014). "Protection against infection was associated with antigen-specific production of IFNγ, TNFα and IL-17 by splenocytes, however, protection against both infection and pathology required the induction of a similar pro-inflammatory response in the respiratory tract draining lymph nodes." (PMID 23613984, 2013). "Similarly, lethal infection of IL-10-deficient mice with the intestinal whipworm parasite Trichuris muris led to increased parasite-antigen-induced IFNγ and IL-17A." (PMID 23345540, 2013). "In Foxp4 cKO mice, the reduced IFNγ production in response to STAg forty days post-infection may be caused by defects in CD4 T cell help." (PMID 22912696, 2012). "The involvement of a cytotoxic response and IFNγ production by IELs in host protection was further confirmed by experiments using adoptive transfer of cells from IFNγ− knockout and perforin knockout mice that proved unable to confer protection from infection in susceptible hosts." (PMID 22807673, 2012). "However, there was a significant decrease in IL-12p70 and IFNγ pulmonary concentrations in Tm-TNF compared to WT mice 322 days post-infection associated with susceptibility of Tm-TNF mice to M. tuberculosis reactivation at this time point." (PMID 22132068, 2011). "Indeed IL-13 has been identified as a susceptibility factor for infection of mice by the protozoan parasite Leishmania major by suppressing the expression of IFNγ and IL-12." (PMID 21573182, 2011). "Since the infection of TLR2/4 double-deficient mice with C. pneumoniae generated even more CD4+IFNγ+ T-cells, we conclude that in vivo antigen-presenting cells are not impaired in their ability to activate antigen-specific T-cells in the absence of TLR2 and TLR4." (PMID 22096480, 2011). "Rather, the persisting infection with L. major[pcosP46] causes an increased IFNγ release." (PMID 20345655, 2010). "However, current diagnostic tools, such as interferon-gamma release assays (IGRAs) and tuberculin skin tests (TSTs), have limited ability to distinguish between different stages of TB or to predict the progression from infection to active disease." (PMID 40491837, 2025). "The inability of IFNγ gene-knockout mice to control C. parvum infection was associated with reduced recruitment of macrophages and T cells to the lamina propria, suggesting this cytokine and immune cells play an important role in the control of the infection in mice." (PMID 40006709, 2025). "The data in BALB/c mice are consistent with our previous studies in CBA/J mice demonstrating that following infection with C. neoformans, cda1∆2∆3∆-vaccinated mice had increases in pulmonary cytokines and chemokines often associated with Th1-type responses, including IFNγ and TNFα." (PMID 38980038, 2024). "Thus, the weak increase of IDO1 in IPP at the peak of infection that subsequently intensified at 11–12 dpi could be linked to the increase of IFNγ observed only during the resolution of infection." (PMID 38756777, 2024). "Indeed, infection of IL-10-/- mice with P. chabaudi chabaudi led to exacerbated pathology which was linked to increased expression of pro-inflammatory cytokines such as IFNγ, IL-12 and TNF." (PMID 35464430, 2022).
infection (continued). "Now, several years later, in the collaborative cross mouse model, researchers have succinctly uncoupled the magnitude of IFNγ expression and subsequent control of Mtb, where a proportion of genotypes evaluated for Mtb susceptibility had low IFNγ production but still controlled the infection." (PMID 35359957, 2022). "Furthermore, mice deficient for the single IP subunits LMP2 or LMP7 showed increased susceptibility to T. gondii infection and displayed less IFNγ-secreting CD8+ T cells following infection although they had similar numbers of activated CD8+ T cells compared to WT mice." (PMID 33968021, 2021). "The early response of the innate immune system in chickens within 1 week post-SE infection is characterized by the upregulation of genes associated with “defense/pathogen response”, inflammation, NK cell-mediated cytotoxicity and production and secretion of the cytokine IFNγ." (PMID 34404469, 2021). "However, because IFNγ-KO mice are much more susceptible than β2-m KO, we speculate that IFNγ is acting in multiple ways to mediate resistance to infection with 17XNL strain." (PMID 32913355, 2020). "Overall, our data demonstrated that IL-17A-deficiency enhanced IFNγ production during infection, supporting the hypothesis that IL-17A plays an important role in downregulating IFNγ at the site of infection during the lung migratory phase of N. brasiliensis infection." (PMID 32636457, 2020). "While our data demonstrate that both IFNγ and IL-17 production was reduced by ILCs in IL-23-deficient mice, we also do not exclude the role of T cells in C. jejuni-induced intestinal pathology especially during later stages of infection when adaptive immune response takes place." (PMID 33488580, 2020). "Thus, the improved control of parasite growth in the absence of type I IFN signaling was dependent on CD4+ T cells and IFNγ but came at the cost of more rapid development of tissue pathology associated with the acute inflammation generated in the first 14 days of infection." (PMID 32101732, 2020). "Although infections are typically attributable to neutropenia in MDS patients, those with IO may also have reductions in key immune cytokines (e.g., TNFα, IFNγ), impaired nitric oxide production, and loss of T-cell function, which can further contribute to infection risk." (PMID 30719392, 2018). "However, IFNγ-deficiency elevated parasitaemia on 3–6 and 16–23 days post Py17x infection." (PMID 30254309, 2018). "This suggests that VIP levels, similarly to mitochondrial function, may be more affected by the cytokine environment than pathogen density, as we previously have shown that the C. rodentium density is similar between WT and IFNγ deficient infected mice at day 10 post infection." (PMID 30252907, 2018). "Thus, under infection states, and perhaps in AA, IFNγ-stimulated MΦs drive HSC loss." (PMID 27621733, 2016). "Our study conclusively demonstrates a key role of IFNγ for early immune defense against M. ulcerans infection in vivo, as mice lacking this cytokine suffered from an accelerated and more severe pathology associated with a significantly higher bacterial burden after 5 weeks of infection." (PMID 26863011, 2016). "Here we show that an early and primary effect of type I IFN during Mtb infection is the cell-intrinsic impairment of IFNγ signaling." (PMID 41659471, 2026). "Cytokines with the greatest contributions to PC1 included IL‐6, IL‐1β, and IFNγ, particularly among samples with secondary infection." (PMID 41488232, 2026). "The immune response during the first weeks of infection is predominantly a Th1 type immune response, involving the release of cytokines such as IL‐12 and IFNγ." (PMID 41546136, 2026). "SBTI donors were associated with an increased TH1 IFNGhigh:TH1/TFH ratio among the cytokine producing cells, paralleling previous observations that hybrid immunity (SARS-CoV-2 vaccination and infection) increases frequencies of IFNγ-releasing CD4 T cells." (PMID 41384750, 2026).